CYP11A1 (cytochrome P450 family 11 subfamily A member 1)
Diseases named in the same sentence as CYP11A1 in open-access papers (continued):
Sharing a sentence is not in itself a finding about the gene and the disease.
cancer (22 papers, 2013 to 2025). A tumor composed of atypical neoplastic, often pleomorphic cells that invade other tissues. "Mito significantly inhibited the migration of cancer cells by more than 75% whereas AMG only caused 30% wound closure compared with that in untreated CYP11A1-overexpressing Caki-1 cells (60% wound closure)." (PMID 38036976, 2023). "The cholesterol side-chain cleavage enzyme (CYP11A1) is closely associated with steroidogenesis, and its downregulation is linked to adrenal dysfunction and several types of carcinoma." (PMID 38036976, 2023). "Recent studies have shown that deficiencies in CYP11A1 expression can lead to fatal adrenal failure if left untreated and are associated with downstream regulation in various cancer types." (PMID 36182900, 2022). "Nevertheless, the key regulators underlying the CYP11A1-mediated suppression of cancer cell proliferation still warrant further investigation." (PMID 36182900, 2022). "A rapid decrease in mesenchymal protein levels in the cancer cell line indicates that CYP11A1 overexpression is associated with inhibiting cancer cell mobility." (PMID 36182900, 2022). "In conclusion, this study identifies posaconazole as a promising CYP11A1 inhibitor with potential applications in cancer immunotherapy and other conditions characterized by elevated steroidogenesis." (PMID 40454094, 2025). "Targeting CYP11A1, the first and rate-limiting enzyme in steroid biosynthesis, has shown promise in cancer therapy, but safe and effective inhibitors remain an unmet need." (PMID 40454094, 2025). "As mentioned in the results section, CYP11A1 plays important roles in cell migration, cytotoxicity, and ferroptosis, especially in cancer cells." (PMID 38036976, 2023). "First, a panel of 1374 natural compounds was tested for cancer inhibition in the CYP11A1-overexpressing Caki-1 cell line model using a wound healing assay." (PMID 38036976, 2023). "Our results showed that CYP11A1 activation inhibited the migration of cancer cells, promoted ferroptosis, and triggered autophagy signaling." (PMID 38036976, 2023). "We also observed a significant increase in the levels of another autophagy protein, Beclin1, in cancer cells, which is consistent with the upregulation of CYP11A1 expression and expression of LC3A/B was also tested." (PMID 38036976, 2023). "The wound width was approximately 75% of the initial width in CYP11A1-transfected Caki-1 cells, indicating that CYP11A1 overexpression highly inhibited cell migration, specifically in cancer cells." (PMID 36182900, 2022). "Decreased expression of CYP11A1 influences the biosynthesis of steroid hormones and is related to several cancers." (PMID 36182900, 2022). "This in vitro transfection system has been used for the molecular mechanism study of CYP11A1 effects on the inhibition of cancer cell mobility and proliferation." (PMID 36182900, 2022). "Recent evidence suggests that CYP11A1 is also significantly downregulated in numerous types of cancer, including liver, colon, kidney, prostate, lung and uterine corpus endometrial carcinoma." (PMID 34208589, 2021). "To clarify the role of this gene in tumorigenesis, we first used Y1 cancer cells derived from a steroidogenic tissue and expressing Cyp11a1 at high level." (PMID 23756599, 2013). "Finally, CYP11A1-derived secosteroids exhibit anti-cancer activities that vary depending on the specific cell type and lineage involved." (PMID 39199241, 2024). "We hypothesized that the remarkably impaired cancer cell proliferation could be related to CYP11A1-induced ferroptosis." (PMID 38036976, 2023). "Significant downregulation of CYP11A1 has been reported in kidney and five other cancers." (PMID 38036976, 2023). "The L_cancer patient prognosis features and risk score were calculated as: KNG1 × 0.621 + CYP11A1 × 0.600 + SMPD1 × 1.370 + DAND5 × 0.859 + NKPD1 × 0.721 + RP11-59D5_B.2 × 0.568 + CTD-2184C24.2 × 0.514 + RP11-680F8.3 × 0.517 − RP11-51F16.9 × 0.731 + CTD-2012K14.8 × 0.765." (PMID 36419007, 2022).
cancer (continued). "Cytotoxicity was measured to determine the inhibitory effect of CYP11A1 in cancer cells." (PMID 36182900, 2022). "Recent studies have shown that CYP11A1 is downregulated in various cancer types." (PMID 36182900, 2022). "CYP11A1 is expressed in the ovaries, testes, adrenal cortex and placenta, lungs, brain, gastrointestinal tract, immune cells, breasts, bones, prostate, and some cancer cells." (PMID 34208589, 2021). "Summarizing, the presented relations between the CYP11A1-RORα/γ and progression of tumor suggest that initiation of the alternative vitamin D metabolism pathway may play a crucial role in cancer progression and prognosis." (PMID 34208589, 2021). "It will be interesting to determine whether Cyp11a1 is expressed in infiltrating T cells in human cancer, if 22(R)-HC is generated in appreciable amounts and, if so, whether this leads to neutrophil recruitment." (PMID 32998240, 2020). "As the alternative vitamin D metabolism pathway via CYP11A1 is just beginning to be understood, its role in cancer and the relative contributions of VDR and ROR are largely unknown." (PMID 29657326, 2018). "Moreover, given the observed decline in the expression of CYP27B1, VDR, CYP11A1, and RORα/γ during cancer progression, as previously discussed, the utility of VD-based treatments may be confined to early rather than advanced stages of the disease." (PMID 38689243, 2024). "The recently identified as non-canonical pathways of vitamin D activation are initiated by CYP11A1, an essential enzyme in steroidogenesis present in various organs and tissues, including the skin, peripheral tissues, adrenal glands, placenta, gastrointestinal tract, and diverse cancer cells." (PMID 39199241, 2024). "Targeting CYP11A1 might offer a new perspective on cancer prevention and treatment." (PMID 36182900, 2022). "Additionally, because the expression levels of CYP27B1, VDR, CYP11A1, and RORα/γ in cancer cells progressively decline during cancer progression the effectiveness of vitamin D-based therapy may be limited to only early stages, but not late stages, of cancer." (PMID 29657326, 2018). "Altogether, HSD3B1, HSD3B2, CYP11A1, CYP11B1, CYP17A1, and CYP3A43, hereby defined as APUC-6, demonstrated tissue- and cancer stage–specific interactions, with the most notable interaction in metastatic PC." (PMID 39207857, 2024). "In combination with BLM for cancer, abnormal expression of STAR, CYP11A1, and HSD3B1 led to hormone secretion disorder." (PMID 38137018, 2023). "Moreover, the metabolites produced from the CYP11A1-driven alternative vitamin D metabolism pathway have been shown to be a biased agonist of VDR with less calcemic effect while retaining anti-proliferative properties in cancer comparable to those of calcitriol." (PMID 29657326, 2018). "Our identification of Cyp11a1+ steroidogenic mast cells within the TNBC TME posits them as instrumental in producing immunomodulatory steroids, aiding the immune escape tactics of cancer cells, possibly by inducing tolerance in DCs." (PMID 40287432, 2025). "CYP11A1-overexpressing Caki-1 cells showed sustained activation of JNK and p38 along with inhibition of p-ERK and p-C-Raf, supporting our hypothesis that CYP11A1-induced oxidative stress may activate JNK-p38 pathways, specifically promoting apoptosis in the cancer cell line." (PMID 36182900, 2022).
infection (7 papers, 2006 to 2026). The state of being infected such as from the introduction of a foreign agent such as serum, vaccine, antigenic substance or organism. "Next, to investigate changes in CYP11A1 protein caused by H. pyloriWT infection, we used laser confocal microscopy to directly observe immunofluorescence staining of anti-CYP11A1 and anti-TOM20 antibodies." (PMID 39113698, 2024). "We concluded that CYP11A1 may be continuously transcriptionally upregulated due to a lack of mitochondrial CYP11A1 protein caused by its redistribution induced by CagA-CYP11A1 interaction under the infection of H. pyloriWT." (PMID 39113698, 2024). "First, the mitochondrial isolation assays further revealed that the CYP11A1 translocated outside the mitochondria and accumulated in the cytoplasm under H. pyloriWT infection." (PMID 39113698, 2024). "This interaction hinted to us that a redistribution occurred in either CagA or CYP11A1 under H. pyloriWT infection." (PMID 39113698, 2024). "The findings indicated that H. pyloriWT infection not only led to an increase in the expression of CYP11A1 protein, but also resulted in a shift in its subcellular localization from the mitochondria to the cytoplasm." (PMID 39113698, 2024). "Although H. pyloriWT infection significantly upregulated the expression of CYP11A1, it was noteworthy that the majority of CYP11A1 would be redistributed outside the mitochondria and thus rendered inactive." (PMID 39113698, 2024). "In stable transgenic lines of tobacco expressing cDNA of CYP11A1 gene, the average areas of affected sites on the leaves on 10th days after infection were approximately 12 times smaller than that in control plants." (PMID 29143658, 2017). "The results revealed that CYP11A1 and CagA could interact with each other in GC cells with H. pyloriWT infection." (PMID 39113698, 2024). "However, this transcription upregulation of CYP11A1 by H. pyloriWT remains contradictory to the cholesterol accumulation under H. pyloriWT infection." (PMID 39113698, 2024). "However, CYP11A1 upregulated by H. pyloriWT was shown to downregulate cholesterol, contradicting cholesterol accumulation under H. pyloriWT infection." (PMID 39113698, 2024). "Thus, the paradoxical phenomenon of simultaneous upregulation of cholesterol and cholesterol-catabolic CYP11A1 in the presence of H. pyloriWT infection was well explained." (PMID 39113698, 2024). "Furthermore, H. pyloriWT infection and CagA were found to promote CYP11A1 at the transcriptional level." (PMID 39113698, 2024). "We determined the level of expression of p16, p18 and p21 after infection by qRT-PCR and we found that while the amount of p16 and p18 transcripts does not change (data not shown), p21 expression increases significantly upon reduction of Cyp11a1 levels." (PMID 23756599, 2013). "However, infection of theca cells with the AF-1 activating function mutant unable to be phosphorylated by MAP kinases consistently led to a higher induction of CYP11A1, STAR, and INSL3 transcription." (PMID 17176485, 2006). "Furthermore, the mitochondrial cholesterol content was negatively associated with the expression of CYP11A1 in GC cells without H. pyloriWT infection." (PMID 39113698, 2024). "Furthermore, CYP11A1-overexpression could no longer decrease CYP19A1 once infected by H. pyloriWT, while CYP11A1-knockdown could still up-regulate CYP19A1 in GC cell with H. pyloriWT infection, indicating H. pyloriWT may exert an indirect impact on CYP19A1 expression via CYP11A1." (PMID 39113698, 2024). "Upon infection of the primary cells with sh-Cyp11a1 vector, but not with mock vector, we observed a reduction in Cyp11a1 expression, which was accompanied by a decrease in cell viability (−30 % versus control GFP)." (PMID 23756599, 2013).
infection (continued). "Interestingly, we found that the regulation of CYP11A1 by CYP19A1 was utterly disrupted in the presence of H. pyloriWT infection, with CYP11A1 remaining at a high level without the impact of CYP19A1 in response to H. pyloriWT infection." (PMID 39113698, 2024). "Given that H. pyloriWT infection could contribute to cholesterol accumulation via targeting CYP11A1 redistribution, we also examined these markers in GC cells with CYP11A knockdown or overexpression under H. pyloriWT infection or not." (PMID 39113698, 2024). "In contrast, H. pyloriWT infection partly disrupted the negative impact of CYP11A1 on CYP19A1: CYP11A1 knockdown could still upregulate CYP19A1; CYP11A1 by PCR overexpression could not downregulate CYP19A1 and WB." (PMID 39113698, 2024). "In addition, H. pyloriWT infection totally disrupted the negative impact of CYP19A1 on CYP11A1: CYP11A1 was immune from the influence of CYP19A1 and could maintain a high expression level in GC cells infected with H. pyloriWT." (PMID 39113698, 2024). "In growth curve experiments, viral-mediated Cyp11a1 knock-down decreased the growth rate of GH3 cells, while infection with the mock vector had not effect on cell growth." (PMID 23756599, 2013). "As these cells were difficult to transfect, we generated a lentiviral vector expressing both a small hairpin (sh) RNA molecule directed against rat Cyp11a1 and the green fluorescent protein (GFP) to monitor infection efficiency (ca. 80 %, data not shown)." (PMID 23756599, 2013).
bacterial infection (1 paper, 2019). "In summary, we conclude that bacterial infection or LPS exposure-induced ROS decrease progesterone production in porcine granulosa-lutein cells by inhibiting StAR, CYP11A1, and 3β-HSD expressions." (PMID 31178965, 2019).
brain diseases (1 paper, 2023). "Other bioactive oxysterols of the retina, such as 27-OHC and 27-COOH, as well as neurosteroïds, such as pregnenolone, which is already a matter of interest for brain diseases and is a product of the CYP11A1 enzyme also expressed in the retina, will deserve further investigations in the future." (PMID 38983043, 2023).
kidney diseases (1 paper, 2022). "They include numerous genes associated with kidney diseases, such as Chga/Chgb, Ptprn, Nphs1/Nphs2, Nsf, Rph3a, Podxl and Cyp11a1." (PMID 36130284, 2022).
neurodevelopmental disorder (1 paper, 2025). A behavioral and cognitive disorder with onset during the developmental period that involves impaired or aberrant development of intellectual, motor, or social functions. "In a mouse model showing aberrations in placental Cyp11a1 expression, a key factor in steroid hormone synthesis, neurodevelopmental disorders in offspring were observed." (PMID 40776983, 2025).
CYP11A1 also shares sentences with these, for which no sentence is quoted: adrenocortical tumors (3 papers); Hypertension (3); adrenoleukodystrophy (2); Cell Renal Cell Carcinoma (2); Cushing syndrome (2); dyslipidemia (2); Hirsutism (2); Hypercholesterolemia (2); ovarian failure (2); premature ovarian failure (2); 21-hydroxylase deficiency (1); 3-beta hydroxysteroid dehydrogenase deficiency (1); adenoma (1); adrenal cancer (1); adrenal crisis (1); anovulation (1); bladder cancer (1); Breast Invasive Carcinoma (1); campomelic dysplasia (1); cervical cancer (1); childhood asthma (1); cholesterol metabolism disorder (1); cutaneous melanoma (1); disorders of sex development (1); endocrine disorders (1); Failure to thrive (1); Fanconi anaemia (1); female infertility (1); fibrosis (1); glioblastoma multiforme- (1).
A further 44 diseases each share a sentence with CYP11A1 in 1 paper.